TBCB (tubulin folding cofactor B)
Description:
Binds to alpha-tubulin folding intermediates after their interaction with cytosolic chaperonin in the pathway leading from newly synthesized tubulin to properly folded heterodimer. Involved in regulation of tubulin heterodimer dissociation. May function as a negative regulator of axonal growth (By similarity).
Synonyms: CG22; CKAP1; CKAPI
Tractability: PROTAC: UniProt records ubiquitination sites on it; ubiquitination databases record sites on it; its protein half-life has been measured.
Gene: Protein-coding gene on chromosome 19 (36,114,289 to 36,125,947, forward strand). Ensembl gene ENSG00000105254.
Subcellular location: Cytoplasm; Cytoplasm, cytoskeleton
Subcellular location (Human Protein Atlas): Cytosol
Pathways (Reactome):
Metabolism of proteins: Post-chaperonin tubulin folding pathway
Gene Ontology:
Molecular function: protein binding; microtubule plus-end binding; alpha-tubulin binding
Biological process: cytoplasmic microtubule organization; post-chaperonin tubulin folding pathway; tubulin complex assembly
Cellular component: cytoplasm; cytosol; cell cortex; microtubule cytoskeleton; microtubule plus-end; nucleus; cytoskeleton
Genetic constraint (gnomAD): Loss-of-function variants: 18 observed, 24.88 expected, observed/expected ratio (o/e) 0.72, 90% interval 0.5 to 1.07. The synonymous counts are far from expectation, so gnomAD's model fits this gene poorly and the ratio says little. Missense variants: 336 observed, 307.48 expected, observed/expected ratio (o/e) 1.09, 90% interval 1 to 1.2. Synonymous variants: 172 observed, 122.25 expected, observed/expected ratio (o/e) 1.41, 90% interval 1.24 to 1.6.
Homologues: Orthologues: chimpanzee TBCB (100% identical), macaque TBCB (99% identical), dog TBCB (94% identical), rabbit TBCB (93% identical), guinea pig TBCB (92% identical), pig TBCB (90% identical), rat Tbcb (90% identical), mouse Tbcb (89% identical), tropical clawed frog tbcb (68% identical), zebrafish tbcb (62% identical), Drosophila melanogaster Tbcb (41% identical).
Diseases named in the same sentence as TBCB in open-access papers:
TBCB is named in the same sentence as 6 diseases in open-access papers, as found by Europe PMC text mining. Sharing a sentence is not in itself a finding about the gene and the disease. The quoted sentences say what the papers report.
cataract (1 paper, 2025). Partial or complete opacity of the crystalline lens of one or both eyes that decreases visual acuity and eventually results in blindness. "Across all cataract groups, actin and microtubule cytoskeletal proteins (ACTN4, DCTN1, TUBA1C, TBCB, TUBB4A) were significantly downregulated compared to controls, with the most marked suppression in ARC." (PMID 41283652, 2025). "Specifically, proteins including ACTN4, DCTN1, MYO18A, TUBA1C, TBCB, and TUBB4A, were downregulated in all cataract groups compared to controls." (PMID 41283652, 2025).
cancer (3 papers, 2017 to 2024). A tumor composed of atypical neoplastic, often pleomorphic cells that invade other tissues. "TBCB has previously been implicated in cancer, but only little is known about its involvement in BC." (PMID 39335143, 2024). "TBCB has a critical role in regulating microtubule dynamics and is overexpressed in many cancers." (PMID 28393858, 2017). "The expression of NUBP2, PLCB3, PPP1CA, TBCB, and UBE2C were positively correlated with PPP1R14B in the majority of cancer types." (PMID 34858479, 2021). "No study has yet investigated TBCB or DDB2 isoforms in connection with cancer." (PMID 39335143, 2024).
tumor (2 papers, 2017 to 2023). "Based on our findings above, we studied whether TBCB is implicated in HILI-regulated tumor cell proliferation, migration and invasion." (PMID 28393858, 2017). "Therefore, increased cell proliferation and inhibited apoptosis of tumor cells may also contribute to the poor outcome of AML patients highly expressed TBCB." (PMID 37476188, 2023).
infection (1 paper, 2022). The state of being infected such as from the introduction of a foreign agent such as serum, vaccine, antigenic substance or organism. "WB and PCR showed that the TBCB protein and mRNA levels were significantly increased in the overexpression group of TBCB, indicating a successful infection." (PMID 36385945, 2022).
TBCB also shares sentences with these, for which no sentence is quoted: giant axonal neuropathy (2 papers); breast carcinoma (1).